PTH (parathyroid hormone)
Diseases named in the same sentence as PTH in open-access papers (continued):
Sharing a sentence is not in itself a finding about the gene and the disease.
Hypocalcemia (continued). "Many studies tried to find an explanation to female predisposition to post-thyroidectomy hypocalcemia and, although the specific mechanism is not certain, the gender disparity may be related to effects of sexual steroids on PTH secretion." (PMID 34575224, 2021). "However, cinacalcet use in chronic diarrheas might be problematic due to sustained PTH suppression, which can impair bone mineralization even if hypocalcemia is prevented with calcium supplementation." (PMID 33400691, 2021). "During routine examinations, he was noted to have hypocalcaemia with a total serum calcium level of 1.30 mmol/L (normal range, 2.11–2.52 mmol/L) and a serum phosphate level of 1.66 mmol/L (normal range, 0.85–1.51 mmol/L), while the serum PTH level was 705 pg/ml (normal range, 15-65 pg/ml)." (PMID 33422028, 2021). "Regional citrate anticoagulation may cause a negative calcium balance, systemic hypocalcemia and parathormone (PTH) activation but randomzed studies are not available." (PMID 34895160, 2021). "However, current literature suggests that PTH evaluation 3–4 h after thyroidectomy may be optimal for predicting post-operative hypocalcemia." (PMID 34574074, 2021). "Besides, ΔPTH is a good predictor of hypocalcemia, even slightly better than PTH." (PMID 34956363, 2021). "Furthermore, PTH levels can be followed to guide early postoperative treatment with calcium and/or cholecalciferol supplements to decrease the incidence and severity of hypocalcemia." (PMID 34429957, 2021). "However, serum PTH levels may remain stable within the first days after thyroidectomy and day 1 PTH levels may be accurate enough to predict hypocalcemia and direct the initiation of calcium supplementation." (PMID 34575224, 2021). "While demonstrated to be highly effective in reducing PTH levels, calcimimetics are only indicated for CKD patients on haemodialysis, with studies of these agents in CKD Stage G3–G4 showing an increased risk of hypocalcaemia and hyperphosphataemia in these patients." (PMID 34170509, 2021). "However, the equivalent levels of postoperative serum PTH and Ca during the first 3 days postsurgery in patients exhibiting hypocalcemia may prove that the postoperative day 1 PTH levels are accurate enough to direct the initiation of Ca supplementation." (PMID 32802056, 2020). "Moreover, hypomagnesemia, another common electrolyte complication in critically ill patients, could impair PTH secretion and thus has been suggested as a possible contributor to hypocalcemia." (PMID 33227914, 2020). "Hypocalcemia may be due to inhibition of PTH action and impaired calcium mobilization from bone." (PMID 32509580, 2020). "A probable explanation could be intravenous infusion of calcium which is very frequently given to these patients when they present with tingling and/or twitching based on presumption that hypocalcemia is a cause without testing for calcium or PTH." (PMID 31360455, 2019). "Mild-to-moderate calcidiol deficiency did not associate with hypocalcemia or high PTH." (PMID 31374914, 2019). "Thus, high serum magnesium levels can decrease PTH and contribute to hypocalcemia." (PMID 30540559, 2019). "The hypocalcemia in pancreatitis is hypothesized to be due to increased calcitonin, calcium sequestration by peripancreatic fat and free fatty acids, and through hypomagnesemia induced PTH resistance." (PMID 31508432, 2019). "Calcitriol deficiency associated with hypocalcemia but not with high PTH." (PMID 31374914, 2019). "Severe calcidiol deficiency associated with high PTH but not with hypocalcemia." (PMID 31374914, 2019). "Furthermore, we also investigated whether preoperative vitamin D levels would affect the accuracy of postoperative PTH in predicting post-thyroidectomy hypocalcemia." (PMID 29100453, 2017). "Hence, vitamin D deficiency did not affect the accuracy of postoperative PTH in predicting hypocalcemia in the present study." (PMID 28955671, 2017).
Hypocalcemia (continued). "Therefore, one could postulate that, in children in whom PTH production is already severely affected, further impact on PTH secretion and resistance may explain the significant hypocalcaemia observed in this cohort during intercurrent illness." (PMID 28993435, 2017). "There is, however, a mechanism that has been proposed to be a key event in the association between anticonvulsants and the lack of bone mass: antiepileptic drugs may interfere with intestinal absorption of calcium, which can lead to hypocalcemia and feedback hypersecretion of PTH." (PMID 26633479, 2015). "Despite assumed higher feed intake in healthy cows, this might be related to a higher ability of healthy cows to respond to the developing hypocalcemia by secreting parathyroid hormone, enabling Ca mobilization from bone, as well as enhanced renal reabsorption and efficient intestinal absorption." (PMID 26479481, 2015). "Therefore, chronic hypocalcemia should result in a concomitant increase in PTH secretion." (PMID 26622568, 2015). "Finally, after a 2-month course of oral cholecalciferol supplementation (50,000UI), PTH levels normalized, suggesting that high PTH might have been secondary to the mild hypocalcemia and sub-normal levels of 25OH - vitamin D." (PMID 26537508, 2015). "Finally, there is also a related disorder termed PHP type 2, which is characterized by hypocalcemia, PTH resistance, absence of AHO, and no GNAS mutations." (PMID 25219572, 2015). "Previously published work by our group indicated that a postoperative PTH level < 9 pg/ml, drawn 1 hour after total thyroidectomy, accurately correlated with the development of significant hypocalcemia, leading us to believe that a simpler protocol could be developed." (PMID 24476535, 2014). "After adjusting for other significant factors, PTH-SC (odds ratio 2.49, 95 % confidence interval 1.52–4.07, p < 0.001) and parathyroid autotransplantation (odds ratio 3.23, 95 % confidence interval 1.22–8.60, p = 0.019) were the two independent factors for hypocalcemia." (PMID 22968355, 2013). "We also did not have data on parathyroid hormone levels which could be elevated in states of vitamin D deficiency and hypocalcemia." (PMID 24205288, 2013). "Therefore, a low 25-OHD may only have a minor or weak effect on hypocalcemia even when PTH-SC is <1.5 pmol/L, and conversely, a normal 25-OHD level may not be able to compensate for the low qPTH level in preventing hypocalcemia." (PMID 22968355, 2013). "However, PTH-SC and parathyroid autotransplantation remained independent factors for hypocalcemia." (PMID 22968355, 2013). "Although hypocalcemia and hyperphosphatemia were found to be associated with the highly elevated PTH levels at 10 weeks of age in Oed mice and now at 6 & 9 months in this study, hypocalcemia and hyperphosphatemia did not occur at 12 & 15 months in Oed mice and the reason(s) for this are unclear." (PMID 23284784, 2012). "Various factors may argue for the replacement of vitamin D deficiency in patients with pHPT: suboptimal dietary intake of vitamin D is known to stimulate parathyroid adenoma growth unrelated to hypocalcaemia and active vitamin D (1-25OH2D) levels and reduces the calcaemic response to PTH." (PMID 23781299, 2012). "Although hypocalcemia was associated with the moderate elevation in PTH in Sml mice at 12 and 15 months, hyperphosphatemia was not seen and indeed the mice were hypophosphatemic relative to their respective controls, and the reason(s) for this is are not clear." (PMID 23284784, 2012). "Therefore, PTH-SC might not only be more accurate and reliable in predicting clinically relevant hypocalcemia than serial Ca monitoring, it might also eliminate the need for drawing blood multiple times and an overnight stay." (PMID 22399155, 2012).
Hypocalcemia (continued). "Furthermore, by comparing mice with targeted disruption of the PTH or 1α(OH)ase genes with PTH-1α(OH)ase double null mice, we found that PTH−/−1α(OH)ase−/− mice died of tetany with severe hypocalcemia by 3 weeks of age with severe defects in skeletal development." (PMID 21966280, 2011). "A more likely scenario is that the increase in PTH levels and parathyroid hyperplasia observed in these animals is mediated by the Ca-sensing receptor, again protecting systemic Ca levels, because the suppressed 1,25(OH)2D levels would lead to persistent hypocalcemia." (PMID 21234310, 2010). "Intravenous administration of potent bisphosphonates usually leads to hypocalcaemia and secondary hyperparathyroidism (which are mild and transient in many cases, but may persist for a long time in others), with serum PTH level increase depending on the status of vitamin D." (PMID 18506177, 2008). "Marked acute increases in PTH were observed during TPE, likely in an effort to protect against acute hypocalcemia." (PMID 40663633, 2026). "Hyperphosphatemia and hypocalcemia, resulting from impaired renal activation of vitamin D, trigger increased production of FGF-23 and parathyroid hormone (PTH), leading to renal secondary hyperparathyroidism (RSHP)." (PMID 41295735, 2025). "Hypocalcemia is a common complication after parathyroidectomy in SHPT patients, resulting from bone remineralization triggered by rapid decline of PTH." (PMID 41367906, 2025). "Hypoparathyroidism is an endocrine disorder characterized by insufficient secretion of parathyroid hormone (PTH), presenting with hypocalcemia, hyperphosphatemia, and a relatively high urinary calcium excretion." (PMID 41465179, 2025). "Hypoparathyroidism (HP) is a rare disease characterized by the absence or inappropriately low concentrations of circulating parathyroid hormone (PTH), leading to hypocalcaemia and hyperphosphataemia." (PMID 40423237, 2025). "Based on the results of this study, higher PTH concentrations also occurred in canine AKI, presumably as a result of the ionized hypocalcemia and hyperphosphatemia reported in these patients." (PMID 40005891, 2025). "Higher PTH concentrations also occurred in canine AKI, as reported in canine CKD and human AKI, presumably as a rapid response to ionized hypocalcemia and hyperphosphatemia, frequently reported in our patients." (PMID 40005891, 2025). "Pseudohypoparathyroidism (PHP) is a rare endocrine disorder due to end-organ resistance to parathyroid hormone (PTH), resulting in hypocalcemia and hyperphosphatemia despite elevated PTH levels." (PMID 41170251, 2025). "Receiver operating curves (ROCs) with area under the curve (AUC) values for pre-operative intact parathyroid hormone (iPTH) and pre-operative alkaline phosphatase (ALP) levels against hypocalcemia were used to determine cutoffs." (PMID 39860385, 2025). "However, hypocalcemia does not always meet a parathyroid hormone (PTH) value under the range, and some studies have also shown that a decrease in calcemia of 1 mg/dL compared with the pre-operative value is associated with hypocalcemia symptoms." (PMID 40568916, 2025). "The method most commonly used to detect postoperative hypocalcemia and HPT is still the second-generation intact PTH assay." (PMID 40786097, 2025). "In comparison with preoperative PTH, preoperative ALP was considered a better predictor of postoperative hypocalcemia." (PMID 40517023, 2025). "Due to the severity of PHPT and the abrupt postoperative drop in PTH, the patient developed hungry bone syndrome (HBS), with persistent hypocalcemia requiring intravenous calcium and oral calcitriol." (PMID 41293386, 2025). "The condition is a consequence of intraoperative damage to the parathyroid glands (PGs) or their vascular supply, resulting in an impaired parathyroid hormone (PTH) secretion and subsequent hypocalcemia." (PMID 38304463, 2024).
Hypocalcemia (continued). "SHPT, characterized by elevated parathyroid hormone (PTH), hypocalcemia, and hyperphosphatemia, affects cardiovascular, nervous, skeletal, blood, and other systems." (PMID 38974573, 2024). "Surgical technique plays a significant role in reducing rates of postoperative hypocalcaemia, as evidenced by the fact that inadvertent parathyroidectomy remains an independent common predictor of both POD 1 low PTH and calcium levels." (PMID 39649119, 2024). "Nonsurgical hypoparathyroidism, a rare endocrine disorder, is characterized by low parathyroid hormone (PTH) levels, leading to hypocalcemia and hyperphosphatemia." (PMID 38929327, 2024). "Here, we investigate the impact of induced subclinical hypocalcemia (SCH) on 5-HT and parathyroid hormone (PTH) concentrations in early-lactation dairy cows under conditions of 24-h milk stasis." (PMID 39650027, 2024). "This case is notable because it demonstrates that sarcoidosis can lead to elevated levels of 1,25-dihydroxyvitamin D independently of parathyroid hormone (PTH), correcting hypocalcemia in a patient with hypoparathyroidism." (PMID 39416579, 2024). "Additionally, a study in rats 17 investigated the effects of a thyroid-parathyroidectomy on enamel development and observed that the intervention induced severe hypocalcemia, affecting the enamel shape and mineralization, which suggests that ameloblasts may be sensitive to PTH." (PMID 38922252, 2024). "Biochemically, VDDR1A presents elevated parathyroid hormone (PTH) and high-alkaline phosphatase (ALP) with normocalcemia or hypocalcemia." (PMID 39452491, 2024). "The measurement of PTH alone during surgery or in combination with serum calcium measurement may guide the decision to discharge or follow up in the hospital, prescribe oral calcium supplementation, or take a more aggressive approach to prevent and treat hypocalcemia." (PMID 40071247, 2024). "This stimulus to PTH release is increased in CKD stages 4 and 5 (GFR <30 ml/min) because hypocalcemia and hyperphosphatemia become persistent in those stages." (PMID 39364464, 2024). "Clinically, iPPSD3 patients have been characterized by parathyroid hormone (PTH) resistance, leading to hypocalcemia and hyperphosphatemia." (PMID 39736869, 2024). "Hypoparathyroidism is a rare endocrine disorder defined by low or inadequate amounts of circulating parathyroid hormone (PTH), which results in hypocalcemia (low serum calcium levels)." (PMID 38646308, 2024). "The incidence of postoperative temporary parathyroidism and hypocalcemia in the NIRAF group was also lower than that in the control group, and postoperative PTH recovery in the NIRAF group was faster than that in the control group." (PMID 36793275, 2023). "Specificity of post operative 4 h PTH and change in PTH was found to be 100% and 78.6% respectively, and PPV of 100% and 91.4% in predicting biochemical hypocalcemia." (PMID 37636752, 2023). "In laboratory tests, low or undetectable serum levels of parathyroid hormone (PTH), hypocalcaemia, and hyperphosphatemia are remarkable and were present in all reported cases of hypoparathyroidism." (PMID 38136332, 2023). "Post operative 4 h PTH and Specificity of 88% and NPV of 86% vitamin D has 84% specificity in predicting symptomatic hypocalcemia." (PMID 37636752, 2023). "As CKD progresses, several biochemical changes occur, including hyperphosphatemia, hypocalcemia, increased fibroblast growth factor 23 (FGF-23) and PTH levels, as well as vitamin D concentrations." (PMID 37122165, 2023). "SHPT is characterized by increased synthesis and secretion of PTH from parathyroid glands in progressive CKD in response to systemic alteration of mineral homeostasis, such as hyperphosphatemia, hypocalcemia, and reduced 1,25(OH)2D3." (PMID 36293076, 2022).
Hypocalcemia (continued). "Given the mechanism whereby hypocalcemia develops soon after surgery in patients with SHPT, it is likely that the preoperative PTH concentrations of the hypocalcemic group were higher, which would explain the severe bone starvation state in this group." (PMID 36531501, 2022). "Hypocalcemia is a common complication of PTX, manifesting as a sudden reduction in serum PTH concentration following surgery, but a small amount of PTH remains in the circulation." (PMID 36531501, 2022). "In one of the largest published series, Lombardi reported a threshold 4-h PTH level of 10 pg/ml to have too high a high false negative to allow safe early discharge, while Sahli reported 1-h PTH levels to not accurately predict patients at risk of hypocalcaemia." (PMID 35247092, 2022). "Hypoparathyroidism (HP) is an endocrine disorder characterized by insufficient production of parathyroid hormone (PTH) resulting in derangements of mineral homeostasis, including hypocalcemia and hyperphosphatemia." (PMID 36619538, 2022). "The most frequent AEs were elevated serum parathyroid hormone (PTH) level (83.3%), hypocalcemia (54.2%), and hypophosphatemia (45.8%)." (PMID 35784742, 2022). "Pseudohypoparathyroidism (PHP) englobes a heterogeneous group of rare (epi)genetic diseases characterized by kidney resistance to the action of parathyroid hormone (PTH), leading to the presence of hypocalcemia and hyperphosphatemia." (PMID 36686455, 2022). "For POD1 PTH levels 15–19 pg/ml and POD1 calcium ≥ 2.0 mmol/l, the incidence of symptomatic hypocalcaemia and need for intravenous calcium was 5.4% (3/55)." (PMID 35247092, 2022). "Hypocalcaemia was recorded in 10% of the siblings who also had significantly lower 25OHD and higher ALP and PTH when compared to normocalcaemic sibling with vitamin D deficiency." (PMID 36111298, 2022). "Regarding ICGA and ioPTH in predicting postoperative hypocalcemia, Our study suggests that ioPTH 3, and relative ioPTH decline could allow an early prediction of postoperative hypocalcemia, with a similar predictive ability to PTH on POD 1, which is in agreement with a recent systematic review." (PMID 35813620, 2022). "Among patients with POD1 PTH levels ≥ 20 pg/ml and POD1 calcium ≥ 2.0 mmol/l, the incidence of symptomatic hypocalcaemia was 1% (3/300), and need for intravenous calcium 0.3% (1/300)." (PMID 35247092, 2022). "Forty-nine patients (75.38%) were considered to have hypocalcemia, and 16 patients (24,62%) were considered to have HPT, both with a higher percentage in Group 2 (85.71% for Ca and 21.42% for PTH)." (PMID 35928728, 2022). "Also, the relative contribution of hypocalcemia, hypophosphatemia, and elevated PTH levels to muscular manifestations of rickets and osteomalacia is not entirely clear, although vitamin D deficiency alone without elevated PTH levels has been reported." (PMID 33553992, 2021). "Similar to VDDR1a, patients show hypocalcemia, hypophosphatemia, and elevated ALP and PTH serum levels with low concentrations of 25(OH)D." (PMID 34199067, 2021). "Bone metabolic abnormalities are reported in some cases, such as hypophosphatemia, hypocalcemia, low 25-OH Vitamin D, and elevation of FGF23, PTH and ALP, as well as hyperphosphaturia." (PMID 34360805, 2021). "Biochemical tests showed hypocalcaemia, hypophosphatemia, phosphaturia, and high serum ALP and PTH levels with normal vitamin D." (PMID 32926064, 2020). "We examined in vivo the impact of FGF23 on the Ca2+/PTH relationship during normocalcemia and acute hypocalcemia in the rat and demonstrated that FGF23 has an inhibitory tonus on PTH secretion, when plasma Ca2+ is within the normal range." (PMID 33233840, 2020). "With regard to CKD progression, several hormonal and biochemical changes such as hyperphosphatemia, hypocalcemia, increased fibroblast growth factor 23 (FGF-23), and PTH levels as well as vitamin D concentration abnormalities have been suggested." (PMID 33193760, 2020).